MCL1 (MCL1 apoptosis regulator, BCL2 family member)
Diseases named in the same sentence as MCL1 in open-access papers (continued):
Sharing a sentence is not in itself a finding about the gene and the disease.
osteosarcoma (continued). "Thus, it is possible that flavopiridol-mediated up-regulation of FBXW7 may be, at least in part, responsible for the decrease in MCL-1 protein levels observed in some osteosarcoma cell lines." (PMID 29805751, 2018). "Also, miR-133a has been shown to target and downregulate MCL1 in osteosarcoma." (PMID 29361709, 2018). "Regarding the molecular mechanism underlying the oncolytic adenovirus-mediated MCL1 suppression, we demonstrated that OBP-301 upregulated MCL1-targeted miRNAs, such as miR-15, miR-16 and miR-29, and miR-29 overexpression efficiently suppressed MCL1 expression in human osteosarcoma cells." (PMID 27356624, 2016). "We next wanted to determine if early osteosarcoma metastases are dependent on MAPK signaling and/or MCL1 in vivo." (PMID 37676378, 2024). "Of particular interest, an MCL1-specific inhibitor, AZD5991, markedly reduced metastatic colonization of osteosarcoma cells." (PMID 37676378, 2024). "Paediatric solid tumour cell lines, namely rhabdomyosarcoma, Ewing sarcoma, osteosarcoma, and neuroblastoma cell lines were co-dependant on BCL-XL and MCL-1 for survival." (PMID 35201512, 2022). "Similar to endometrial cancer and osteosarcoma, use of siCDK9 and LDC000067 resulted in a dose-dependent inhibition of cell-viability and a decrease in pS2 of RNAP II, MCL-1 levels and an increase in BAX expression and PARP cleavage." (PMID 34062779, 2021). "Lower levels of miR-1 and miR-133b in canine osteosarcoma tissues were found to increase tumorigenesis through a higher expression of their target genes MET and MCL1." (PMID 33008041, 2020). "Our results suggest that flavopiridol treatment is cytotoxic at the nanomolar range in all osteosarcoma cell lines analyzed and can effectively decrease the expression of several anti-apoptotic BCL-2 family members, including MCL-1." (PMID 29805751, 2018). "Results showed that expression of BCL2L2, MCL-1, IGF1R, MET, phospho-Akt and FAK were significantly decreased in miR-133b over-expressed osteosarcoma cell lines U2-OS and MG-63." (PMID 24391788, 2013). "These indicate that miR-133b play a role as a tumor suppressor gene in osteosarcoma through inhibiting PI3K/Akt signaling and down-regulating several anti-apoptotic molecules and oncogenes such as BCL2L2, MCL-1, IGF1R, MET, and FAK." (PMID 24391788, 2013). "Further, to better understand the mechanisms how miR-133b regulates cellular phenotypes of osteosarcoma cells, we first measured the expression of BCL2L2, MCL-1, IGF1R and MET, which are identified as the target genes of miR-133b in several cancers." (PMID 24391788, 2013). "The western blotting results showed that over-expression of miR-133b decreased the expression of BCL2L2, MCL-1, IGF1R and MET in osteosarcoma cells U2-OS and MG-63." (PMID 24391788, 2013). "Over-expression of miR-133b in osteosarcoma cell lines U2-OS and MG-63 decreases the expression of BCL2L2, MCL-1, IGF1R, MET and FAK, leading to the inactivation of Akt." (PMID 24391788, 2013). "Further, the depletion of Mcl-1 rapidly destabilized TCTP in an osteosarcoma cell line U2OS, supporting the conclusion that Mcl-1 serves as a chaperone of TCTP, binding and stabilizing TCTP in vivo." (PMID 22570787, 2012). "Western blot analysis demonstrated that Bcl-XL, survivin, and MCL-1 were constitutively overexpressed in drug sensitive cell lines and MDR osteosarcoma cell lines." (PMID 20459702, 2010). "Expression of Stat3, phosphorylated Stat3 (pStat3) and Stat3 targeted proteins, including Bcl-XL, Survivin and MCL-1 were determined in drug sensitive and MDR osteosarcoma cell lines and tissues by Western blot analysis." (PMID 20459702, 2010). "Chemotherapeutic agents, including methotrexate, cisplatin and doxorubicin, are widely employed in osteosarcoma treatment, but their anticancer efficacy may be hindered by anti‐apoptotic proteins such as BCL‐2, MCL‐1, c‐FLIP and XIAP." (PMID 40889216, 2025).
osteosarcoma (continued). "While co-inhibition of BCL-2 and BCL-xL failed to induce osteosarcoma cell death, co-inhibition of MCL-1 with either BCL-2 or BCL-xL led to rapid apoptosis, underscoring the predominant role of MCL-1 in osteosarcoma cell survival." (PMID 39497108, 2024). "MCL-1 expression has also been associated with resistance to agents targeting BCL-2 and/or BCL-xL, however the osteosarcoma cells survived dual ABT-199/A-1331852 exposure regardless of their MCL-1 expression levels." (PMID 39497108, 2024). "In contrast, we confirmed that MCL1 functioned as the target of miR-320a for ameliorating DDP resistance in CC, which was consistent with the previous study that miR-320a/MCL1 axis mediated the doxorubicin resistance of osteosarcoma." (PMID 35444548, 2022). "Additionally, OIP5-AS1 and SNHG12 were involved in osteosarcoma doxorubicin resistance via miR-200b-3p/FN1 and miR-320a/MCL1 pathways, respectively." (PMID 33639865, 2021). "Mechanistically, miR-26a directly targets the pro-survival protein myeloid cell leukemia 1 (MCL1), and in turn, the enforced expression of MCL1 markedly antagonizes miR-26a-decreased MDR in osteosarcoma MDR cells, therefore demonstrating that miR-26a reverses MDR in osteosarcoma by targeting MCL1." (PMID 33816494, 2021). "In this study, by investigating clinical osteosarcoma samples and MDR osteosarcoma cell lines, we show that MiR-26a functions to reverse MDR in human osteosarcoma, wherein the targeted expression of myeloid cell leukemia 1 (MCL1) represents a critical mechanism." (PMID 33816494, 2021). "This indicates that the increased MCL-1 protein levels in U2OS, and perhaps also in other osteosarcoma cells, may be a result of protein stabilization and decreased degradation." (PMID 29805751, 2018). "While other studies have proposed that an increase in E2F1 expression could mediate the transcriptional repression of MCL-1, we were unable to detect changes in E2F1 protein levels upon flavopiridol treatment in osteosarcoma." (PMID 29805751, 2018). "To investigate the underlying mechanism of OBP-301-mediated MCL1 suppression, we determined whether OBP-301 upregulates MCL1-targeted miRNAs (miR-15, miR-16, miR-29) via E2F1 activation in human osteosarcoma cells." (PMID 27356624, 2016). "Additional research studies of osteosarcoma have demonstrated that miR-375 may function through interactions with Autophagy related gene 2B (ATG2B) and Myeloid leukemia cell differentiation protein (Mcl-1)." (PMID 36674758, 2023). "By contrast, although the anti-apoptotic member Mcl-1 may be a putative target of miR-491-5p, this miRNA did not influence Mcl-1 expression in any of the three osteosarcoma cell lines investigated." (PMID 35337159, 2022). "In osteosarcoma, it was found that the microRNA-29 family may play a tumor inhibitory role in controlling methotrexate resistance and apoptosis by targeting COL3A1 or MCL1 apoptosis regulators." (PMID 35047627, 2021). "Of note is the observation that the restoration of MCL1 largely rescues the miR-26a-reversed MDR in osteosarcoma, suggesting that there exist other mechanisms that may be responsible for miR-26a regulation in MDR in osteosarcoma." (PMID 33816494, 2021). "SNHG12 is higher in Dox-resistant osteosarcoma cells than in sensitive cells and correlates with lower patients’ survival: specifically, SNHG12 induces resistance by up-regulating the mir320a/myeloid cell leukemia 1 (MCL1) axis that protects from the apoptosis induced by Dox." (PMID 32599901, 2020).
neuroblastoma (52 papers, 2008 to 2025). Neuroblastoma (NB) is the most common solid, extracranial childhood tumor. "Knockdown or biochemical inhibition of the spliceosome component U2 snRNP SF3B1 also favors MCL1 splicing toward the pro-apoptotic MCL1S variant and sensitizes MCL1-dependent neuroblastoma cells to ABT-737." (PMID 29361709, 2018). "Here, we have demonstrated that Aurora A inhibition not only leads to mitotic arrest but also leads to loss of p4E-BP1 in MYCN-amplified neuroblastoma cells (resulting in downregulation of MCL-1 as a result of cap-dependent translation inhibition)." (PMID 26859456, 2016). "We verified that MLN8237 and VX680 treatment each resulted in loss of p4E-BP1 and MCL-1 in MYCN-amplified neuroblastoma cells, as did knockdown of Aurora A." (PMID 26859456, 2016). "In the course of PCR analyses of Mcl1 mRNA variants in human neuroblastoma cells we amplified an mRNA species that carries a 45 bp deletion in the Mcl1L coding region from SH-EP neuroblastoma cells." (PMID 23872733, 2013). "Resveratrol caused neuroblastoma cell cytotoxicity with S-phase arrest, decreased clonal expansion, and increased mitochondria-mediated intrinsic caspase-dependent apoptosis by selectively targeting cyclin D1, Bcl-2, Bcl-xL, and Mcl-1 proteins." (PMID 38249515, 2023). "Similarly, MCL-1 is also frequently expressed in medulloblastoma [~50% of tumours,] and in neuroblastoma, where high expression is associated with a high-risk phenotype." (PMID 35568716, 2022). "In contrast to their neuroprotective effect in specific post-mitotic neuron models, CDK inhibitors may have opposite effects in neuroblastoma and other proliferating neuronal cell lines where they cause downregulation of Mcl-1 and lead to apoptosis." (PMID 30401820, 2018). "Therefore, it is likely that both mitotic arrest and loss of p4E-BP1-mediated cap-dependent protein translation contribute to the loss of MCL-1 following MLN8237 treatment in MYCN-amplified neuroblastoma cells." (PMID 26859456, 2016). "Expression of this Mcl1 variant may therefore represent an adaption of tumor cells to avoid extrinsic death signaling and may thereby serve as a diagnostic and/or therapeutic gene in neuroblastoma and other malignancies." (PMID 23872733, 2013). "Our recent study in MYCN-amplified neuroblastoma revealed that MP1 also targets MYCN (a MYC homologue) along with MCL-1, leading to autophagy stimulation and energy metabolism inhibition." (PMID 38200580, 2024). "Both DOXY-sel cell lines exhibited downregulation of several proteins associated with poor neuroblastoma prognosis, including HIF-1α, P-gp, or MCL-1." (PMID 37973789, 2023). "MCL1 knockout, while synergizing with multiple chemotherapeutics in neuroblastoma cell lines, also promotes cytotoxicity in our outgroup; for example, it also has strong synergy with doxorubicin in our cardiomyocyte cell line." (PMID 37957169, 2023). "In line with this reasoning, activation of the ISR by thapsigargin was also sufficient to downregulate c-MYC, HIF-1α, and MCL-1 in neuroblastoma cells already within 1 h of treatment, whereas BCL-2 levels remained unchanged." (PMID 37973789, 2023). "In cisplatin-resistant neuroblastoma, however, MCL1 was by far the most promising anti-apoptotic target, with sensitivity to BCL2 and BCL-XL inhibitors lost upon chemoresistance." (PMID 37723317, 2023). "These experiments highlight the importance of MCL1 as promising therapeutic target in chemoresistant neuroblastoma." (PMID 37723317, 2023). "The dual BCL-2/MCL-1 inhibitor TW-37 also successfully induces apoptosis in N-MYC-amplified neuroblastoma in vitro and in vivo, further emphasising that targeting multiple anti-apoptotic BCL-2 family members is necessary to induce apoptosis in some scenarios." (PMID 35568716, 2022). "In vitro, MCL-1 inhibition sensitised neuroblastoma cells to ABT-199 treatment, highlighting the protective role MCL-1 mediates in cells with high BCL-2:BIM complex levels." (PMID 35568716, 2022).
neuroblastoma (continued). "Bim binding patterns to different pro-survival Bcl2 members determine Bcl2- or Mcl1-mediated apoptosis resistance in neuroblastoma." (PMID 34572875, 2021). "By using selective BH3-mimetics, this study demonstrates that BCL-2, BCL-XL, and MCL-1 are all relevant therapeutic targets in neuroblastoma." (PMID 32203216, 2020). "With three out of 14 cell lines responding to S63845, the inhibition of MCL-1 as a stand-alone approach also appears promising in neuroblastoma." (PMID 32203216, 2020). "The combination of MCL1 inhibition with ABT-199 displayed efficacy in neuroblastoma with high BCL2 expression in vitro and in vivo." (PMID 32764384, 2020). "Liraglutide attenuated MG-induced apoptosis in neuroblastoma SH-SY5Y cells through the up-regulations of pro-survival Mcl1 signaling, and Akt and MEK1/2 synthesis." (PMID 32547400, 2020). "Taken together, these data highlight that BCL-XL, BCL-2 and MCL-1 all possess essential antiapoptotic functions in neuroblastoma." (PMID 32203216, 2020). "AT-101, which also neutralizes Mcl-1, was more active against neuroblastoma cells, but concomitant Mcl-1 knockdown further increased potency, suggesting that Mcl-1 antagonism was incomplete." (PMID 30885150, 2019). "ABT-737 has a low binding affinity towards MCL-1 and several resistance cases of ABT-737 as a result of high MCL-1 expression have been described not only in neuroblastoma, but also in other cancers." (PMID 31652776, 2019). "The expression of Mcl-1 and Bcl-2 correlated to clinical prognostic factors and survival in neuroblastoma patients." (PMID 30885150, 2019). "Given that MCL-1 is commonly over-expressed in many cancers, including neuroblastoma, MCL-1 is an attractive target, particularly in combination with other therapies, including chemotherapy and other targeted therapies." (PMID 31455317, 2019). "To summarize, these results indicate that the targeting of MCL-1 by miR-193b contributes to miR-193b-induced cell death in neuroblastoma cells." (PMID 29719597, 2018). "We demonstrated that miR-193b overexpression reduces MCL-1 mRNA and protein expression in neuroblastoma cells." (PMID 29719597, 2018). "The mRNA and protein levels of MCL-1 and Cyclin D1 were reduced upon miR-193b overexpression in all neuroblastoma cell lines tested." (PMID 29719597, 2018). "Previous studies established that neuroblastoma cells are primed to death through sequestration of BIM by either MCL-1 or BCL-2." (PMID 29719597, 2018). "BCL2 and MCL1 expression levels are correlated with the efficacy of BCL2 antagonists in neuroblastoma cells." (PMID 28915653, 2017). "The pro-survival BCL2 proteins BCLXL as well as MCL1 which are both bound by NOXA in neuroblastoma cells inhibit autophagy by sequestration of BECN1." (PMID 28415610, 2017). "It has been reported that BIS expression stabilizes myeloid leukemia cell differentiation protein (MCL)-1 and promotes cellular survival in a neuroblastoma cell line." (PMID 28241425, 2017). "The venetoclax/idasanutlin combination was consistently found to be highly synergistic in a diverse panel of neuroblastoma cell lines, including cells with high MCL1 expression levels." (PMID 28915653, 2017). "MLN8237 further pushes the neuroblastoma cell past the apoptotic threshold through reduction of MCL-1; BCL-xL is ineffective at blocking the ensuing death signal because BCL-xL levels are markedly low." (PMID 26859456, 2016). "In fact, we found that treatment with the TORC1/2 inhibitor MLN0128 led to downregulation of p-4E-BP1 and MCL-1 in MYCN-amplified neuroblastomas, which demonstrated that MCL-1 in these cancers is downregulated following inhibition of p4E-BP1." (PMID 26859456, 2016). "MCL-1 reduction by siRNA sensitized MYCN-amplified neuroblastoma cells to ABT-199, inducing similar levels of apoptosis as the combination treatment in the scrambled (sc) siRNA transfected cells." (PMID 26859456, 2016).
neuroblastoma (continued). "No changes in the expression and activity of BCL-XL were observed after ABT199 treatment, indicating that MCL-1 plays a more important role in neuroblastoma resistance to ABT199 than BCL-XL." (PMID 27056887, 2016). "The induction of apoptosis in MYCN-amplified neuroblastoma cells was mitigated by BIM siRNA, implicating that the disruption of BIM/MCL-1 complexes leads to loss of MCL-1-bound BIM and contributes to ABT-199/MLN8237-mediated apoptosis." (PMID 26859456, 2016). "This analysis uncovered the MCL-1 inhibitor NOXA, encoded by PMAIP1, to be significantly higher in MYCN-amplified neuroblastomas." (PMID 26859456, 2016). "RhEpo has been shown to induce anti-apoptotic genes including Bcl-xL, Bcl-2, and Mcl-1 in Ewing sarcoma and neuroblastoma cell lines." (PMID 22188703, 2011). "Many antiapoptotic proteins, such as Bcl-2, Mcl-1 and Bcl-XL, have been shown to inhibit chemotherapeutic agent-induced apoptosis in diverse cell system models including hematopoietic and neuroblastoma cells." (PMID 20102612, 2010). "Induction of the antiapoptotic protein Mcl-1 cannot be the reason for this low apoptosis reported in resistant neuroblastoma cell lines since the protein is equally expressed in sensitive and resistant cells after bortezomib exposure." (PMID 18534018, 2008). "Additionally, EGFR signaling reportedly regulated Mcl-1 survival action in neuroblastoma by disrupting Bim to Mcl-1." (PMID 38888847, 2025). "Therefore, it would be interesting to further investigate the effectivity of combined MEK and MCL-1 inhibition in neuroblastoma in vivo models." (PMID 36895472, 2023). "While our study focussed on neuroblastoma, previous studies indicate that a similar shift towards MCL1 dependency may be observed in other cancer types as well." (PMID 37723317, 2023). "Yet, our in vitro results suggest that the MCL-1 inhibitor S68345 could also be effective in a subset of neuroblastoma tumors with lower BCL-2 levels, where BIM is bound to MCL-1." (PMID 36895472, 2023). "Finally, while our combination therapy approach using MCL-1 inhibitors/barasertib combination therapy showed a significant extension of life in an animal model of neuroblastoma, these benefits were relatively modest." (PMID 37958555, 2023). "Besides the inhibition of BCL2 with ABT199, also the inhibition of BCL-XL or MCL1 with their selective antagonists A1331852 or S63845 is able to induce apoptosis in multiple neuroblastoma cells including primary cells." (PMID 37723317, 2023). "Taken together, these experiments provide a first and exciting indication that the combination of MCL1 inhibition together with NK cell-based immunotherapy may be highly promising for the treatment of chemoresistant neuroblastoma." (PMID 37723317, 2023). "In addition to hematological malignancies where Mcl-1 is the major target, Myc-driven diseases such as neuroblastoma are a trending area for the development of CDK9 inhibitors, with a few compounds being actively tested in the clinic." (PMID 35383271, 2022). "Furthermore, recent research demonstrated that dual inhibition of BCL-XL and MCL-1 synergistically reduces viability and induces death in neuroblastoma cell lines displaying treatment resistance to individual BCL-2, BCL-XL, or MCL-1 inhibitors." (PMID 35568716, 2022). "To study how inhibition of BCL-XL or MCL-1 may initiate cell death in neuroblastoma, we selected cell lines sensitive to A1331852 (IMR-32) or S63845 (Kelly)." (PMID 32203216, 2020). "Here, we investigated the role of BCL-2, BCL-XL and MCL-1 in neuroblastoma." (PMID 32203216, 2020). "In this situation, MCL-1 may play an essential role in sequestering partially active BAK, thus representing a novel Achilles heel for cancer cell survival and opening up novel applications of MCL-1 inhibitors like S63845 for the treatment of neuroblastoma." (PMID 32203216, 2020).